CD55 (CD55 molecule (Cromer blood group))
Diseases named in the same sentence as CD55 in open-access papers (continued):
Sharing a sentence is not in itself a finding about the gene and the disease.
ovarian carcinoma (5 papers, 2005 to 2025). A malignant neoplasm originating from the surface ovarian epithelium. "Our studies identify a therapeutic mechanism for treating platinum resistant ovarian cancer by blocking CD55 nuclear entry." (PMID 38853277, 2024). "Membrane-bound CRPs (mCRPs), such as CD46, CD55, and CD59, are expressed by ovarian cancer tumors and cell lines." (PMID 34359708, 2021). "In ovarian cancer, the neutralization of CD46, CD55, and CD59 in combination with the anti-HER2 monoclonal antibodies trastuzumab and pertuzumab induces tumor cell killing in vitro." (PMID 34359708, 2021). "The immunoblotting experiments showed that the cultured ovarian cancer cells can shed the C regulators CD46, CD55 and CD59 into the culture medium." (PMID 15726105, 2005). "To investigate whether the tumour cells' relative resistance to C could be due to the expression of membrane regulators CD46, CD55 and CD59, we performed immunohistochemical analysis of tumour cells isolated from two patients with ovarian cancer." (PMID 15726105, 2005).
prostate carcinoma (5 papers, 2016 to 2025). A carcinoma that arises from epithelial cells of the prostate gland. "We also identified a higher percentage of subclonal cell populations in aggressive taxane resistance prostate cancer subtypes overexpressing CD55 and CD109." (PMID 37476073, 2023). "In accordance, CD55 was shown to be functionally active in human prostate cancer cell lines (PC-3) and to inhibit complement-mediated lysis in a manner dependent on its expression." (PMID 34572075, 2021). "In particular, the expression of CD55 and CD59 on PrC cells may be associated with promoting cell survival and contributing to the metastatic potential of prostate cancer cells." (PMID 40733075, 2025). "The emerging hypothesis was that upregulation of CD55, and subsequent inhibition of complement-mediated lysis, leads to cancer cell survival and promotes prostate cancer metastasis." (PMID 34572075, 2021). "ML-60218 also induces CD55, which has been found to promote prostate cancer growth and survival." (PMID 30820548, 2019). "Furthermore, CD55 also promotes prostate cancer cell survival and metastatic lesion formation." (PMID 37476073, 2023). "Overexpression of CD55 has been assessed in clinical specimens from patients with advanced prostate cancer, compared to normal non-malignant prostate and in clear cell renal carcinoma." (PMID 34572075, 2021).
Sepsis (5 papers, 2013 to 2025). Sepsis is defined as life-threatening organ dysfunction caused by a dysregulated host response to infection. "In this study, we identified 8 senescence-related genes (IGFBP7, GMFG, IL10, IL18, ETS2, HGF, CD55, and MMP9) and developed a diagnostic model for the prediction of sepsis occurrence." (PMID 38259686, 2023). "A comprehensive analysis was conducted to investigate the impact of senescence-related genes on sepsis, and 8 hub genes (IGFBP7, GMFG, IL10, IL18, ETS2, HGF, CD55, MMP9) associated with senescence were identified." (PMID 38259686, 2023). "Our results indicate that NOD2-mediated signals enhance C5a generation by suppressing CD55 expression on neutrophils through IL-1β-dependent or IL-1β-independent IL-10 production during polymicrobial sepsis." (PMID 23675299, 2013). "SB203580, a receptor-interacting protein 2 (RIP2) inhibitor downstream of NOD2, reduced C5a generation by enhancing CD55 expression on neutrophils, resulting in attenuation of polymicrobial sepsis." (PMID 23675299, 2013). "Here, we demonstrate that NOD2 enhances C5a generation by IL-10-mediated suppression of CD55 expression on neutrophils, thereby aggravating polymicrobial sepsis." (PMID 23675299, 2013). "In conclusion, NOD2-mediated signals increase C5a levels by suppressing CD55 expression on neutrophils via IL-1β-dependent or IL-1β-independent IL-10 production by neutrophils, thereby aggravating sepsis." (PMID 23675299, 2013). "Taken together, these data suggest that NOD2-mediated IL-1β-dependent and/or IL-1β-independent IL-10 production enhances C5a generation by suppressing CD55 expression on neutrophils, thereby aggravating sepsis." (PMID 23675299, 2013). "Soluble CD55 administration reduced C5a generation and increased the survival rates of WT and Nod2−/− mice injected with rIL-10 during sepsis." (PMID 23675299, 2013). "Moreover, SB203580 administration to WT mice increased CD55 expression levels in F4/80−Ly-6G+ neutrophils, and increased survival rates during sepsis." (PMID 23675299, 2013). "Moreover, rIL-10 or rIL-1β administration to Nod2−/− mice decreased CD55 expression on peritoneal F4/80−Ly-6G+ neutrophils during sepsis." (PMID 23675299, 2013). "Thus, to functionally link the expression of these molecules to NOD2-mediated C5a generation during sepsis, CD55 and CR1/2 expression levels on gated peritoneal F4/80−Ly-6G+ neutrophils and F4/80+Ly-6G− macrophages were measured." (PMID 23675299, 2013). "Consensus cluster analysis we successfully classified sepsis patients into two distinct groups based on the expression of 8 hub genes (IGFBP7, GMFG, IL10, IL18, ETS2, HGF, CD55, and MMP9)." (PMID 38259686, 2023). "Activation of the complement system is enhanced during sepsis and RBCs are protected by membrane surface proteins like CD35, CD55 and CD59." (PMID 35966861, 2022). "Furthermore, we found that NOD2-mediated IL-10 production by neutrophils enhanced C5a generation by suppressing CD55 expression on neutrophils in IL-1β-dependent and/or IL-1β-independent manners, thereby aggravating CLP-induced sepsis." (PMID 23675299, 2013). "Peritoneal F4/80+Ly-6G− macrophages minimally expressed CD55 and CR1/2 in WT and Nod2−/− mice with CLP, suggesting that expression modulation of these molecules on macrophages minimally contributes to NOD2-mediated C5a generation during sepsis." (PMID 23675299, 2013). "Notably, the key genes upregulated during sepsis are responsible for regulating cell cycle progression and differentiation (i.e., S100A8 and S100A9) and immune responses (i.e., ANXA1, APOBEC3A, LILRA5, CR1, and CD55)." (PMID 37298316, 2023). "Alternatively, compensatory generation of C3a in the complement cascade may account for the relative lack of a change in C3a level during sepsis, even though altered CD55 expression inhibits C3a and C5a convertase equally in vivo." (PMID 23675299, 2013).
Sepsis (continued). "However, the altered CD55 expression on neutrophils affected C5a, but not C3a generation in the NOD2-mediated pathogenesis of sepsis, although CD55 inhibits both C3a and C5a convertase." (PMID 23675299, 2013). "Furthermore, considering the CD55 expression levels on neutrophils from WT, Il-1r−/−, Il-10−/−, and Nod2−/− mice with CLP, it is conceivable that NOD2-mediated IL-10 production suppresses CD55 expression on peritoneal neutrophils during sepsis in both IL-1β-dependent and IL-1β-independent manners." (PMID 23675299, 2013). "Thus, it is questionable how reduced CD55 expression on neutrophils inhibits the generation of C5a rather than C3a, in NOD2-mediated pathogenesis of sepsis." (PMID 23675299, 2013).
autoimmune disease (4 papers, 2006 to 2024). A disorder resulting from loss of function or tissue destruction of an organ or multiple organs, arising from humoral or cellular immune responses of the individual to their own tissue constituents. "In contrast, it has been reported that mice deficient of CD55 have accelerated autoimmune disease, an effect that is thought to be attributable mainly to the missing complement-regulating function of CD55 in these mice." (PMID 17007638, 2006). "Decay accelerating factor (DAF, CD55), a glycosylphosphatidylinositol-anchored membrane protein, is a candidate for autoimmune disease susceptibility based on its role in restricting complement activation and evidence that DAF expression modulates the phenotype of mice models for autoimmune disease." (PMID 16626483, 2006). "As a crucial regulator of the complement system, CD55 has been widely studied in autoimmune diseases." (PMID 30473747, 2018). "In some autoimmune diseases, CD55 expression and function are impaired." (PMID 30473747, 2018). "However, data concerning regulation of CD55 in autoimmune diseases are very limited." (PMID 30473747, 2018).
Autoimmunity (4 papers, 2006 to 2022). The occurrence of an immune reaction against the organism's own cells or tissues. "Genetic variation, such as SNPs, in the BEN-2 region may influence expression of both CR2 and CD55 in tandem, thereby exacerbating the effect of variants in their contributions to autoimmunity." (PMID 35769482, 2022). "NZB and DBA/2 mice have reduced and elevated CD55, respectively, and exposure to HgCl2 exacerbates autoimmunity in NZB while DBA/2 mice are resistant." (PMID 24592327, 2014).
liver cancer (4 papers, 2020 to 2025). An epithelial or non-epithelial malignant neoplasm that arises from the liver. "The combination of CD55‐TMn and Dox exerted a synergistic effect and can more effectively inhibit growth of liver cancer via promoting cell pyroptosis and cell apoptosis." (PMID 33251723, 2020). "Cytokines such as TNF-α, IL-6, and IL-1β can increase CD55 expression in liver cancer cells." (PMID 40596619, 2025). "CD55 and CCND1 are reportedly associated with cancer progression, as demonstrated in liver cancer." (PMID 37745301, 2023).
Nephropathy (4 papers, 2016 to 2025). A nonspecific term referring to disease or damage of the kidneys. "Interestingly, complement‐regulating proteins such as CD55 were suppressed in adenine‐induced nephropathy." (PMID 41324413, 2025). "Interestingly, the gene expression of the complement regulatory protein CD55 (Cd55) was significantly downregulated in adenine‐induced nephropathy." (PMID 41324413, 2025).
pancreatic cancer (4 papers, 2015 to 2025). "CD55 is involved in the dedifferentiation, invasiveness, migration, and metastasis of tumors and association with pancreatic cancer." (PMID 32842508, 2020). "In conclusion, the present study indicated that CD97 and its ligand CD55 are upregulated in pancreatic cancers and are closely associated with lymph node involvement, metastasis and vascular invasion." (PMID 25624904, 2015). "Taken together, these results indicated that CD97 and its ligand CD55 are upregulated in pancreatic cancers and are closely associated with lymph node involvement, metastasis and vascular invasion." (PMID 25624904, 2015). "Further, Iacobuzio-Donahue confirmed that CD55 is highly expressed in pancreatic cancer when measured by microarrays." (PMID 32842508, 2020). "Complement decay-accelerating factor (CD55) has been identified by immunohistochemistry in pancreatic cancer, and its elevated levels correlate positively with tumour aggressiveness, vascular invasion, and prognosis." (PMID 30404163, 2018). "All 37 pancreatic cancer tissue specimens were CD55+, including 13 tumors with strong CD55 expression and four tumors with uniform CD55+ staining." (PMID 25624904, 2015). "We propose that analysis of the expression of both CD97 and CD55 has a prognostic value for pancreatic cancer." (PMID 25624904, 2015). "The expression of CD55 in pancreatic cancer and adjacent normal pancreatic tissues was investigated." (PMID 25624904, 2015). "In this study, immunohistochemistry was used to analyze CD97 and CD55 protein expression in samples obtained from 37 pancreatic cancer patients." (PMID 25624904, 2015). "Therefore, in this study, CD97 and CD55 expression in pancreatic cancer tissues and adjacent normal pancreatic tissues was investigated with regard to tumor aggressiveness and prognosis." (PMID 25624904, 2015). "Notably, CD97 and CD55 were expressed consistently in pancreatic cancer tissues (r2=0.5422; P<0.05)." (PMID 25624904, 2015). "Thus, analysis of both CD97 and CD55 expression may present potential prognostic value for pancreatic cancer." (PMID 25624904, 2015). "However, the association between CD97 and CD55 expression in pancreatic cancer has not yet been systemically investigated." (PMID 25624904, 2015). "However, strong CD55+ expression was exhibited in the cell membranes in pancreatic cancer tissues." (PMID 25624904, 2015). "However, little is known regarding the roles of CD97 and CD55 in pancreatic cancer." (PMID 25624904, 2015). "CD97 and CD55 were absent or only weakly expressed in the normal pancreatic tissues but strongly expressed in pancreatic cancer tissues (P<0.05), particularly in tissues with lymph node involvement, metastasis or vascular invasion (P<0.05)." (PMID 25624904, 2015).
preeclampsia (4 papers, 2014 to 2025). Preeclampsia is a hypertensive disorder of pregnancy that is characterized by new-onset hypertension with proteinuria presenting after 20 weeks of gestation, and depending on mild or severe forms may initially present with severe headache, visual disturbances, and hyperreflexia. "In a study that measured placental mRNA expression of the complement regulatory proteins in preeclampsia at the time of delivery, a significant upregulation of CD55 and CD59 mRNA expression was observed." (PMID 26556948, 2015).
stomach cancer (4 papers, 2009 to 2022). "An IgM antibody against a tumour‐specific isoform of CD55 has been found to promote gastric tumour regression by inducing apoptosis, without causing severe side effects; therefore, CD55 inhibition, or its use as a ligand to induce apoptosis in lesions, may help to inhibit the progression of IM." (PMID 35851954, 2022).
thrombosis (4 papers, 2024 to 2025). "Serum determination of antiphospholipid antibodies (anticardiolipin and anti-beta 2 glycoprotein antibodies), molecular testing, and CD55 and CD59 flow cytometry are not affected by acute thrombosis or anticoagulant treatment." (PMID 40150064, 2025).
acute lymphoblastic leukemia (3 papers, 2021 to 2026). Leukemia with an acute onset, characterized by the presence of lymphoblasts in the bone marrow and the peripheral blood. "The current study aims at investigating the expression levels of mCRPs; CD46 and CD55 in the acute lymphocytic leukemia and acute myelogenous leukemia and to further elucidate its role in Egyptian cancer patients." (PMID 41526546, 2026). "There were also patients with chronic pulmonary disease in the intensive care unit, acute lymphoblastic leukemia, lipin-1 deficiency (rhabdomyolysis + acute renal failure with hemodialysis), and CHAPLE syndrome (CD55 deficiency)." (PMID 34431642, 2021).
Alzheimer disease (3 papers, 2019 to 2024). A progressive, neurodegenerative disease characterized by loss of function and death of nerve cells in several areas of the brain leading to loss of cognitive function such as memory and language. "Moreover, the overexpression of CD55 inhibits complement activation; this could be of interest in Alzheimer’s disease (AD) since the deposition of complement is observed in the brains of patients with AD." (PMID 39273695, 2024).
colitis (3 papers, 2025). Inflammation of the colon. "Supporting this, CD55-deficient mice exhibit aggravated colitis symptoms." (PMID 40979590, 2025). "However, based on the observation that CD55–/– mice were more susceptible to chemically induced colitis, the authors concluded that upregulation of CD55 may represent an attempt to block excessive complement activation." (PMID 41031890, 2025).
cyst (3 papers, 2020 to 2024). A sac-like closed membranous structure that may be empty or contain fluid or amorphous material. "Thus, the evaluation of CD55 using preoperative EUS-guided cyst fluid is a natural next step in validating the diagnostic value of CD55 as a marker for IPMN dysplasia." (PMID 32842508, 2020). "CD55 concentrations in individual cyst fluid samples were calculated and demonstrated in 2 types of IPMN classification." (PMID 32842508, 2020). "Of the final marker candidates, CD55 was validated using 70 individual cyst fluid samples by ELISA as it evidently differed in expression between the histological groups of IPMN." (PMID 32842508, 2020). "CD55 was validated in 70 cyst fluid samples (22 LGD, 5 HGD, 14 invasive IPMN, 13 MCN, and 16 SCN) by ELISA." (PMID 32842508, 2020). "CD55 was previously reported as a biomarker for IPMN by gene expression microarray experiments and was found to be associated with disease progression in a proteomic profiling study of IPMN cyst fluid." (PMID 36930707, 2023). "Within this system, oncoproteins MUC1 and CD55, along with the oncogene KRAS, are identified in either cyst fluid or blood plasma specimens from a cohort of 39 patients." (PMID 38234100, 2024). "A cohort of 39 samples, comprising 33 cyst fluids and 6 blood plasma specimens, underwent thorough examination utilizing both the SiMoT array – targeting oncoproteins MUC1 and CD55, and oncogene KRAS – and the SIMOA SP‐X planar technology, focused exclusively on MUC1 and CD55." (PMID 38234100, 2024).
dysferlinopathy (3 papers, 2010 to 2024). "An earlier study identified increased susceptibility to complement attack due to down-regulation of DAF1/CD55 and DAF2/CD55b only in dysferlin-deficient muscles, demonstrated by mRNA and protein analyses in dysferlin-deficient mouse models and patients with dysferlinopathy." (PMID 39123261, 2024). "This impact of gender is important to consider for the complement system, since dysf-/- female SJL/J mice were used in the study that reported downregulation of decay accelerating factor /CD55, and fatty replacement of many muscles is more severe in female patients with dysferlinopathy." (PMID 30970035, 2019). "Indeed, in dysferlinopathies, there is evidence of immune system involvement including the presence of muscle inflammation and a down regulation of the complement inhibitory factor, CD55." (PMID 20618995, 2010).
endometrioid tumor (3 papers, 2017 to 2021). A benign, borderline, or malignant epithelial tumor of the female reproductive system characterized by the presence of glands and/or cysts lined by neoplastic cells that resemble endometrial cells. "Collectively, our findings identify CD55 as a unique signaling node that drives self-renewal and therapeutic resistance through a bifurcating signaling axis and provides an opportunity to target both signaling pathways in endometrioid tumors." (PMID 28838952, 2017). "Moreover, two primary uterine endometrioid tumor specimen co-expressed CD55 with a CSC marker (UTE-1 and UTE-2)." (PMID 28838952, 2017). "On the basis of our initial findings in complement-free conditions, we hypothesized that CD55 may regulate self-renewal and cisplatin resistance in endometrioid tumors through a complement-independent mechanism." (PMID 28838952, 2017).
hepatoma (3 papers, 2012 to 2025). "Others have demonstrated that IL-1β also promotes CD55 expression in articular chondrocytes, hepatoma cells, and intestinal epithelial cells." (PMID 22590509, 2012). "Previous studies observed a cytokine-mediated upregulation of CD55 and CD59 expression in human hepatoma cells in tumors mediated via pro-inflammatory cytokines such as tumor necrosis factor-alpha, IL-1 beta, and IL-6." (PMID 40723265, 2025).
idiopathic pulmonary fibrosis (3 papers, 2024 to 2025). Idiopathic pulmonary fibrosis (IPF) is a nonneoplastic pulmonary disease that is characterized by the formation of scar tissue within the lungs in the absence of any known cause. "CD55 or decay accelerating factor (DAF) acts as a protective factor against complement dysregulation, which is linked to the pathogenesis of idiopathic pulmonary fibrosis (IPF)." (PMID 38667308, 2024). "Increased C3a levels also upregulate TGF-β, a key mediator of obliterative bronchiolitis, which downregulates membrane regulatory proteins such as CD46/Crry and CD55 in models of lung fibrosis." (PMID 41217841, 2025). "In the same research, primary normal human alveolar type II epithelial cells (hAECs) purified from six normal and five idiopathic pulmonary fibrosis lungs were immunoblotted with antibodies recognizing CD55." (PMID 39337843, 2024).